VIRMA (vir like m6A methyltransferase associated)
Diseases named in the same sentence as VIRMA in open-access papers (continued):
Sharing a sentence is not in itself a finding about the gene and the disease.
tumor (126 papers, 2018 to 2026). "Further research into the mechanisms by which VIRMA regulates resistance-related genes through m6A modification will help uncover the underlying mechanisms of tumor resistance and provide new therapeutic strategies for chemotherapy-resistant patients." (PMID 40723784, 2025). "VIRMA not only regulates tumor-associated proliferation and metastasis factors but also participates in the activation of classical oncogenic signaling pathways, such as STAT3 and PI3K/AKT, which are crucial for cancer proliferation and metastasis." (PMID 40723784, 2025). "Our study demonstrated that cytokine CCL3, which is secreted by hepatocytes, promotes tumor metastasis by regulating m6A modification via vir-like m6A methyltransferase associated (VIRMA) in ICC cells." (PMID 36691046, 2023). "Considering tumor types, a significant association between VIRMA immunoexpression and SE (p = 0.0017) was depicted." (PMID 30866959, 2019). "Studies have not yet elucidated the mechanism underlying the downstream regulation of VIRMA and whether it occurs through the m6A pathway in several tumor models, which is crucial for the development of treatments." (PMID 33731118, 2021). "The increased expression of VIRMA was associated with higher cancer stages, tumor grade, and nodal metastasis, suggesting that its dysfunction may play an important role in the initiation and progression of HNSCC." (PMID 34209046, 2021). "In all tumor models assessed, the most promising player was shown to be Vir like m6A methyltransferase associated (VIRMA), which could constitute a potential target for personalized therapies." (PMID 30428628, 2018). "Therefore, CCL3/VIRMA/SIRT1 axis may be one of the important mechanisms underlying tumor evolution and metastasis and is a potential new therapeutic target for ICC." (PMID 36691046, 2023). "At the same time, VIRMA regulates genes related to metabolism through m6A modifications, promoting metabolic reprogramming in tumor cells, which enhances their survival ability in the immunosuppressive microenvironment." (PMID 39911396, 2025). "Extensive research has elucidated VIRMA’s dual regulatory mechanisms in tumor progression through both m6A-dependent and independent pathways." (PMID 40723784, 2025). "VIRMA serves as a core component of the m6A methyltransferase complex, demonstrating characteristic overexpression and tumor-specific subcellular localization across multiple malignancies." (PMID 40723784, 2025). "Among all 15 core m6A genes, VIRMA exhibits the highest frequency of abnormalities, with 21.4% of tumor samples showing expression or copy number alterations (e.g., overexpression or amplification), significantly higher than METTL3 (6.2%)." (PMID 40723784, 2025). "In CRC, VIRMA expression was significantly elevated in tumor cells, especially in radioresistant cell lines (such as HCT116R and SW620R), where its expression was further increased." (PMID 40723784, 2025). "VIRMA regulates tumor metabolic reprogramming by influencing key factors in tumor cell aerobic glycolysis." (PMID 40723784, 2025). "According to studies, VIRMA affects the m6A alteration of several immune-related genes, which controls the tumor cells’ resistance to immunotherapy and their capacity to avoid immune detection." (PMID 39911396, 2025). "Mechanistically, VIRMA upregulated LncRNA EBLN3P expression in an m6A-dependent manner, and EBLN3P competed with miR-153-3p to increase VIRMA expression, thereby reducing ferroptosis in tumor cells and enhancing their radioresistance." (PMID 40723784, 2025). "In HNSCC, after VIRMA knockout, most cancer cells were arrested in the S phase, indicating a reduction in the number of dividing tumor cells following VIRMA knockout." (PMID 40723784, 2025). "Upon VIRMA knockdown, ferroptosis in tumor cells significantly increased, characterized by elevated intracellular Fe2+ levels, increased expression of ferroptosis-related protein ACSL4, and decreased expression of SLC7A11 and GPX4." (PMID 40723784, 2025).
tumor (continued). "Increased PD-L1 expression on the surface of tumor cells results from VIRMA’s enhancement of the m6A alteration of immune checkpoint molecules, including PD-L1 mRNA, which improves its stability and translation efficiency." (PMID 39911396, 2025). "To identify the downstream genes that VIRMA regulates to govern tumor occurrence and progression, we conducted Spearman correlation analysis on the RNA-seq data in the TCGA database and selected the top ten genes with the highest correlation coefficient." (PMID 38577917, 2024). "To gain a deeper understanding of the importance of VIRMA in HNSCC, we analyzed VIRMA expression and cancer stage, tumor grade, and nodal metastasis by using the UALCAN online database." (PMID 38577917, 2024). "In the current study, we confirmed that VIRMA is upregulated in HNSCC and further found that VIRMA is a potential prognostic factor affecting tumor growth and lymphatic metastasis in HNSCC." (PMID 38577917, 2024). "VIRMA knockdown (HuCCT1-shVIRMA) led to significantly low tumor growth rate and tumor weight compared with the other groups (HuCCT1: 0.75 ± 0.05 g, HuCCT1-shNC: 0.77 ± 0.02 g, HuCCT1-shVIRMA: 0.28 ± 0.01 g)." (PMID 36691046, 2023). "Significantly, fewer pan-CK-positive tumor cells were observed in the VIRMA-depleted group than those in the control group, indicating that VIRMA silencing decreased the metastatic ratio in inguinal lymph nodes." (PMID 37028765, 2023). "The H&E staining demonstrated that VIRMA knockdown significantly reduced the tumor density and differentiation degree of the ICC." (PMID 36691046, 2023). "To further evaluate the tumor-promoting role of VIRMA in NPC in vivo, we used a subcutaneous tumorigenesis model and an inguinal lymph node metastasis model." (PMID 37028765, 2023). "Subsequently, numerous research proved that VIRMA was abnormally highly expressed in multiple cancer types and contributed to tumor progression." (PMID 37028765, 2023). "Together, these data demonstrated that CCL3 promotes the growth of ICC cells by regulating VIRMA/SIRT1 in ICC subcutaneous tumor mice model." (PMID 36691046, 2023). "UPR, which can be triggered by ER stress, is critical for tumour growth, adaptation and response to chemotherapy but its effect in the presence of VIRMA overexpression in cancer is elusive." (PMID 37208522, 2023). "The immunohistochemistry analyses confirmed that the expression of VIRMA, SIRT1, and Ki67 was upregulated in the tumor tissues with CCL3 stimulation, and it was also reversed in the tumor tissues with VIRMA down-expression." (PMID 36691046, 2023). "The influence of VIRMA overexpression and downstream consequences of m6A methylation changes on tumour microenvironment and chemotherapeutic response in cancer remains to be determined." (PMID 37208522, 2023). "Here, we revealed that VIRMA acted as a tumor-promoting gene to enhance NPC growth and metastasis in an m6A-dependent way." (PMID 37028765, 2023). "With CCL3 stimulation, the Ki67 was up-regulated in the tumor tissues and it was also reversed in the tumor tissues with VIRMA down-expression." (PMID 36691046, 2023). "We demonstrate that VIRMA contributes to NCCIT cells tumor aggressiveness and to cisplatin resistance, both in vitro and in vivo, by regulating DNA damage response." (PMID 34446080, 2021). "Here, VIRMA was expressed at lower levels both in OC tissues and in the high-stage group, indicating its potential function as a tumor suppressor in OC tumorigenesis, which was confirmed in our collected OC tissue samples by PCR and IHC." (PMID 34631700, 2021). "More studies are needed to demonstrate the biological function of VIRMA and its impact on tumor progression and survival, as well as the mechanisms involved, in more cancer types and phenotypes." (PMID 33731118, 2021). "We also found VIRMA to be highly expressed in cisplatin-exposed metastatic tumor samples, suggesting a role in tumor aggressiveness and in cisplatin response, requiring further investigation." (PMID 34446080, 2021).
tumor (continued). "Our data corroborates the oncogenic properties of VIRMA, with its knockdown resulting in reduced tumor cell growth and decreased cell proliferation, as well as decreased cell migration and invasion." (PMID 34446080, 2021). "VIRMA transcript levels were significantly higher in tumor samples that exhibited strong VIRMA (p < 0.0001) and m6A (p = 0.0001) immunoexpression." (PMID 30866959, 2019). "Considering all tumor samples, VIRMA and YTHDF3 mRNA expression levels were positively correlated (rs = 0.44, p < 0.001)." (PMID 30866959, 2019). "Tumor samples with strong VIRMA immunoexpression also displayed significantly higher YTHDF3 transcript levels (p = 0.0303) whereas those with strong YTHDF3 protein expression disclosed a trend for higher YTHDF3 transcript levels (p = 0.0724)." (PMID 30866959, 2019). "Most metastatic tumor samples showed strong VIRMA and YTHDF3 immunoexpression intensity, while weak/moderate staining was observed for m6A." (PMID 30866959, 2019). "By inhibiting VIRMA expression or blocking its m6A modification activity, the expression of PD-L1 and immune suppressive factors can be effectively reduced, restoring immune activity within the tumor microenvironment." (PMID 39911396, 2025). "Further suppressing anti-tumor immune responses, VIRMA also controls the m6A modification levels of chemokines and inflammatory cytokines (like CXCL1 and IL-6), which encourages the growth of myeloid-derived suppressor cells (MDSCs) and regulatory T cells (Tregs) in the tumor microenvironment." (PMID 39911396, 2025). "The subcellular distribution of VIRMA protein is closely related to tumor type and occurrence." (PMID 40723784, 2025). "However, the precise mechanisms governing VIRMA’s subcellular trafficking and its context-dependent functional variations in different tumor microenvironments require further investigation." (PMID 40723784, 2025). "Additionally, VIRMA facilitates immune evasion within the tumor microenvironment via the KLF1-PD-L1 signaling axis." (PMID 40723784, 2025). "This dynamic nuclear-cytoplasmic distribution strongly correlates with tumor malignancy and metastatic potential, suggesting VIRMA localization may serve as a potential tumor grading biomarker." (PMID 40723784, 2025). "Integrating cutting-edge technologies such as single-cell sequencing and spatial transcriptomics may help to map the detailed regulatory role of VIRMA in tumor heterogeneity." (PMID 40723784, 2025). "Targeting VIRMA in combination with chemotherapeutic drugs may significantly improve drug sensitivity and reverse tumor resistance." (PMID 40723784, 2025). "Furthermore, using the UALCAN online database, we found that VIRMA was predominantly highly expressed in 24 types of tumor tissues." (PMID 38577917, 2024). "The results showed that VIRMA was positive in tumor tissue compared to normal tissue." (PMID 38577917, 2024). "To investigate whether VIRMA exerts its tumor-promoting function through upregulating ITGA2, ITGA5, and NTRK1 expression, we performed in vitro functional experiments by overexpressing ITGA2, ITGA5, or NTRK1 in VIRMA-silenced NPC cells." (PMID 37028765, 2023). "In addition, SIRT1 was shown to be a critical downstream target of VIRMA, which fuels tumor metastasis." (PMID 36691046, 2023). "VIRMA has an oncogenic role in other tumor models, including urological malignancies." (PMID 34446080, 2021). "Indeed, VIRMA silencing was shown to decrease m6A deposit during embryonic development, constituting another link to developmental biology in this tumor model." (PMID 34446080, 2021). "Additionally, combining VIRMA inhibitors with immune checkpoint inhibitors could help overcome resistance, enhancing the anti-tumor effects of immunotherapy." (PMID 39911396, 2025). "Moreover, VIRMA-knockdown tumors disclosed significantly lower number of vessels at tumor periphery, both macroscopically and histologically, even when normalizing for tumor size." (PMID 34446080, 2021).
tumor (continued). "For instance, in TGCTs, higher VIRMA expression was found to be associated with low disease stage; in addition, in KCa, RBM15B overexpression (an eraser) associated with advanced disease at diagnosis, whereas the writer METTL3 was reported to act as a tumor suppressor." (PMID 30428628, 2018). "Several studies have shown that VIRMA activates signaling pathways such as PI3K/AKT and Wnt/β-catenin, which enhance tumor cell proliferation and resistance to T cell-mediated cytotoxicity." (PMID 39911396, 2025). "In NSCLC, VIRMA mediated the m6A modification of DAPK3, facilitating YTHDF2/3-mediated DAPK3 post-transcriptional degradation and promoting tumor growth." (PMID 40723784, 2025). "More importantly, single‐cell sequencing data supported that TAX1BP1 is highly expressed exclusively in clusters 3, while lactylation level, VIRMA and SP1 were highly expressed in tumor cells." (PMID 41017455, 2025). "Mechanistically, VIRMA is promoting signaling through the STRA6/STAT3 axis, leading to elevated HIF-1α levels, which in turn enhances glycolysis and drives tumor progression." (PMID 40102715, 2025). "VIRMA was found to enhance the m6A modification and expression of LINC01106 in LUAD, thereby promoting tumor progression." (PMID 40723784, 2025). "In BC, VIRMA upregulation increased the m6A modification level of UPR-related transcripts, enhancing sensitivity to UPR and ER stress, thereby inducing tumor cell death." (PMID 40723784, 2025). "VIRMA upregulated CA9 expression in an m6A-dependent manner in OSCC, and inhibition of VIRMA suppressed tumor growth both in vitro and in vivo." (PMID 40723784, 2025). "Collectively, these findings demonstrate that CAFs secrete circTAX1BP1, which binds to VIRMA in CRC cells, thereby elevating m6A levels and promoting tumor progression." (PMID 41017455, 2025). "A similar mechanism was observed in CC, where VIRMA negatively regulated the mRNA stability of BTG2 via an m6A-YTHDF2-dependent pathway, thereby facilitating malignant tumor progression." (PMID 40723784, 2025). "Immunohistochemical images showed the expression levels of RBM15, VIRMA, YTHDC2, YTHDF2, METTL14, and IGF2BP2 proteins in tumor tissues." (PMID 36791151, 2023). "In this study, we showed that VIRMA was significantly upregulated in ICC tissues, which correlated with poor prognosis and thus regarded as a prognostic factor for tumor recurrence in ICC." (PMID 36691046, 2023). "To explore the effect of the CCL3/VIRMA/SIRT1 pathway on the ICC malignant process, we constructed subcutaneous and orthotopic tumor models in nude mice." (PMID 36691046, 2023). "Tumor growth of HuCCT1 ICC cells was significantly faster than that in the PBS group after CCL3 treatment, while HuCCT1 cells with VIRMA knockdown grew slower even after receiving CCL3 stimulation." (PMID 36691046, 2023). "In conclusion, the results of the current study confirmed that CCL3/VIRMA/SIRT1 pathway promotes ICC proliferation and tumor metastasis in vivo." (PMID 36691046, 2023). "Overall, METTL3, METTL14, VIRMA, and ALKBH5 immunoexpression levels differed significantly between tumor and normal tissues." (PMID 35048498, 2022). "Paradoxically, we found that tumor suppressors were negatively correlated with the infiltration of pDCs, DCs, and cytotoxic cells, and the tumor promoters METTL3, VIRMA, and CBLL1 were positively correlated with Tcm and Th2 cell infiltration." (PMID 35223847, 2022). "This study identified a broad upregulation of these genes in tumor samples as compared to normal tissues, with significant increases in METTL3, METTL14, KIAA1429 (VIRMA), YTHDF1, YTHDF2, ALKBH5, FTO, WTAP, RBM15, and HNRNPC." (PMID 34209046, 2021). "The higher expression of YTHDF1, HNRNPC, IGF2BP1, VIRMA, and HNRNPA2B1, the more characteristics of tumor OV stem cells and the lower the tumor OV differentiation." (PMID 34150845, 2021).
tumor (continued). "To further understand the biology of the three genes, we analyzed the protein expression of IGF2BP1, VIRMA and ZC3H13 in OC in the Clinical Proteomic Tumor Analysis Consortium (CPTAC) samples." (PMID 32950970, 2020). "VIRMA could stabilize KLF1 mRNA, upregulate KLF1 expression, and consequently enhance PD-L1 expression and promote immune evasion by tumor cells." (PMID 40723784, 2025). "In the M6A-dependent pathway, VIRMA regulates key oncogenes (e.g., FOXM1, HK2) and tumor suppressor genes (e.g., RND3, BTG2), affecting the proliferation, metastasis, metabolic reprogramming, and drug resistance of tumor cells." (PMID 40723784, 2025). "VIRMA, in turn, enhanced SOX8 mRNA stability via m6A modification, promoting tumor progression." (PMID 40723784, 2025). "Furthermore, high MCMBP expression correlates with elevated levels of m6A “readers” (IGF2BP1, IGF2BP3) and “writers” (VIRMA, YTHDF3), a state thought to promote tumor progression by enhancing the stability and translation of oncogenic mRNAs." (PMID 41346611, 2025). "The results showed that after VIRMA knockout, cell proliferation, and colony formation were reduced, and HNSCC cells mostly stagnated in the S phase, which meant that the number of tumor cells dividing after VIRMA knockout was reduced." (PMID 38577917, 2024). "Additionally, we observed that most high-expressed m6A regulatory factors in tumor tissues had CNV gains, such as VIRMA, ZNF217, and YTHDF1." (PMID 39020010, 2024). "On the other hand, immunohistochemical staining showed that the expression of tumor progression markers such as N-cadherin, Vimentin, VEGF, Ki67, and Cyclin D1 was decreased along with the downregulation of VIRMA, except E-cadherin exhibited a contrary tendency." (PMID 36691046, 2023). "VIRMA induces m6A methylation of the 3′ UTR of GATA3 pre-mRNA, leading to dissociation of the RNA-binding protein HuR and degradation of GATA3 pre-mRNA, promoting tumor growth and metastasis in vivo." (PMID 35784761, 2022). "The results demonstrated high mRNA expression levels of VIRMA in at least 25% of the tumor samples compared with normal controls, indicating that genomic amplification is not the only mechanism determining VIRMA overexpression." (PMID 32218194, 2020). "Finally, we confirmed both in vitro and in vivo that CCL3 could activate VIRMA and its critical downstream target SIRT1, which fuels tumor metastasis in ICC." (PMID 36691046, 2023). "Notably, tumours with VIRMA amplification exhibited significantly increased expression of VIRMA mRNA compared to samples without profound genetic alteration of VIRMA (Diploid) in both cohorts." (PMID 37208522, 2023). "The results showed that expression levels of METTL3, VIRMA and CBLL1 were significantly increased, while expression levels of METTL14 and ZC3H13 were significantly decreased in HCC, which was closely related to clinicopathological factors, such as tumor stage and prognosis." (PMID 35223847, 2022). "Furthermore, UALCAN revealed that the gene expression differences in METTL3, RBM15, RBM15B, VIRMA and CBLL1 may also be related to tumor grade." (PMID 35223847, 2022). "Therefore, the expression levels of 7 m6A regulators (METTL14, YTHDC2, FTO, ALKBH5, HNRNPA2B1, VIRMA, and RBMX) were lower in both the OC tissues and the high-stage group, indicating their potential function as tumor suppressors in OC tumorigenesis and development." (PMID 34631700, 2021). "However, the protein expression of IGF2BP1 and VIRMA in the normal control group and tumor group was not consistent with the mRNA expression levels." (PMID 32950970, 2020). "However, the protein expression and the mRNA expression of VIRMA in the normal control group and tumor group was not consistent, which suggests that the mRNA may serve as a reservation." (PMID 33731118, 2021).